IL1B (interleukin 1 beta)
Diseases named in the same sentence as IL1B in open-access papers (continued):
Sharing a sentence is not in itself a finding about the gene and the disease.
psoriasis (continued). "In the DEX group, the expressions of IL-1β, IL-6, TNF-α, IL-17, and IL-22 were significantly lower than the model group (p < 0.05), suggesting that the expressions of inflammatory cytokines associated with psoriasis have been inhibited after the intervention of DEX." (PMID 32090080, 2020). "However, they are not included in the major psoriasis susceptibility genes except for the risk loci at IL1B in late onset psoriasis." (PMID 30135860, 2018). "Furthermore, using the imiquimod-induced model of psoriasis, it was found that C3 deficient mice showed significantly reduced levels of IL-1β, TNF-α, IL-17a, and IL-23 in the skin and draining lymph nodes and decreased infiltration of neutrophils." (PMID 29713318, 2018). "Then, we investigated whether CCN1 regulated IL-1β production in mouse models of psoriasis." (PMID 28266627, 2017). "Our observations on an enhanced caspase-5 regulation in the presence of IL-17A and NLRP1 inflammasome activity in keratinocytes suggests a functional contribution for epidermal IL-1β production in psoriasis and likely other diseases, where Th17 may also contribute, such as lupus erythematosus." (PMID 28422993, 2017). "In fact, in a mouse model of imiquimod-induced psoriasis-like inflammation, topical curcumin was demonstrated to improve the skin lesions with an effect comparable to that of clobetasol and to significantly decrease the cutaneous levels of IL-17A, IL-17F, IL-22, IL-1β, IL-6, and TNF-α mRNA." (PMID 26090395, 2015). "Interestingly, there was a general suppression in migratory capacity in the mLCs derived from patients with psoriasis compared with those from healthy controls, with the exception of the IL-1β-stimulated cells, in which migratory capacity was equivalent between the two groups." (PMID 21933242, 2012). "Similar to AD, psoriasis involves keratinocyte-driven activation of the NF-κB, JAK/STAT, and MAPK, which stimulate the production of pro-inflammatory cytokines such as IL-1β, IL-6, and TNF-α." (PMID 41479908, 2025). "SCFAs inhibit the NF–κB pathway and reduce the production of pro-inflammatory cytokines such as IL-1β, IL-6, and TNF-α, which can alleviate skin symptoms in psoriasis, acne, or HS." (PMID 41178942, 2025). "Regarding psoriasis, PPS reduced pro-inflammatory cytokines (IL-6, IL-1β) in both psoriatic keratinocytes and a co-culture model mimicking the skin-adipose tissue interface." (PMID 41226468, 2025). "In vitro experiments confirmed that MDMs derived from psoriasis patients overexpressed pyroptosis-related molecules (Caspase 1 and Caspase 4) as well as pro-inflammatory cytokines (TNFα, IL6, IL1β) when compared to healthy controls." (PMID 40722833, 2025). "Due to the difficulty of obtaining skin samples from clinical patients, the number of psoriasis patients used to verify the skin expression levels of NLRP3 and IL-1β was relatively small." (PMID 41383588, 2025). "To this end, we first examined the expression of IL1B, IL17, IL22 and IFNG, all well-known cytokines involved in the pathogenesis of psoriasis, in the scRNAseq dataset." (PMID 40746860, 2025). "In response to DAMP or PAMP stimulation, keratinocytes can produce a range of proinflammatory cytokines, including IFN-β, IL-1β, IL-36, TNF, IL-6, IL-8, IL-25, and CXCL10, which help establish the inflammatory T cell phenotype characteristic of psoriasis." (PMID 39859462, 2025). "MSC exosomes also suppressed DC maturation and activation and inhibited the release of pro-inflammatory cytokines (TNF-α, IFN-γ, IL-1β), chemokines (CCL20 and CXCL8), and psoriasis-specific cytokines (IL-23)." (PMID 41007656, 2025). "This upregulates the expression of inflammatory cytokines such as IL-1β and TNF-α, thereby promoting the development of psoriasis lesions." (PMID 41383588, 2025). "We identified five cytokines and receptors that intersected between urticaria, atopic dermatitis, and psoriasis: IL36G, IL20, IL1B, CXCR1, and CXCL1." (PMID 40159643, 2025).
psoriasis (continued). "Both strategies have been shown to modulate key cytokines involved in psoriasis, such as TNF-α and IL-1β, which are central to the inflammatory processes driving the disease." (PMID 40243475, 2025). "CCN1, a novel proinflammatory factor and extracellular protein, increases IL-1β production via p38 MAPK signaling, thereby promoting inflammation in psoriasis." (PMID 41385507, 2025). "In turn, hBD-2 in patients with psoriasis or RA increases the production of TNF-α, IFN-γ, IL-10, IL-1β, IL-6, and IL-22." (PMID 40062148, 2025). "qPCR results revealed significantly increased expression of Lcn2, Tnfsf12, Il1b, Krt5, and Krt10 mRNA in the skin of Fn14–/– mice with IMQ-induced psoriasis." (PMID 40369189, 2025). "Materials and Methods: This review synthesizes the current evidence on key salivary cytokines—IL-1β, IL-6, TNF-α, and IL-17—in relation to psoriasis pathogenesis, diagnosis, and treatment monitoring." (PMID 40731810, 2025). "In keratinocytes affected by psoriasis, the build-up of cytoplasmic DNA activates the AIM2 inflammasome, resulting in the secretion of IL-1β and fostering T-cell-mediated skin inflammation." (PMID 40343299, 2025). "In this study, we provide a comprehensive analysis of pyroptosis-related genes (PRGs) in psoriasis, identifying key molecular players such as CASP1, CASP5, AIM2, NOD2, and IL1B that drive the inflammatory response and disease progression." (PMID 40771724, 2025). "On the contrary, treatment with methylene chloride fraction of A. chinensis stalk succeeded to mitigate inflammatory response via reducing IL-1β, IL-6, IL-23, and IL-17 levels by 40, 34, 44, and 51%, respectively, relative to IMQ-induced psoriasis group." (PMID 40072672, 2025). "In our study, the strong increase of IL-1α, TNF-α, IL-1β and S100A7 was observed in psoriasis-like lesions." (PMID 38393364, 2024). "To identify potential therapeutic options for psoriasis and AMI, we screened drugs targeting CXCL8, IL1B, S100A9, and S100A12 using the DsigDB database." (PMID 39014096, 2024). "Proinflammatory cytokines IL-1α, TNF-α, IL-1β and S100A7 have been reported to be up-regulated in psoriatic skins and they are involved in the psoriasis pathogenesis." (PMID 38393364, 2024). "Consistently, the absence of IL-1R attenuated skin thickening and production of IL-1β, IL-17, and IL-23 in IMQ-induced psoriasis model mice." (PMID 39352743, 2024). "Recent studies have suggested that CBD’s effects on skin diseases such as allergic contact dermatitis, acne, and psoriasis are attributed to the inhibition of pro-inflammatory cytokines such as TNF-α, IL-1β, IL-6, and IL-17A." (PMID 39335596, 2024). "Leptin, an adipocyte-derived hormone, as an inflammatory mediator, stimulates the production of chemokines IL-1β and TNF-α from blood monocytes in obese patients with psoriasis." (PMID 39063202, 2024). "Network pharmacology revealed 259 active components targeting pathways in psoriasis, focusing on TNF, IL-6, and IL-1β." (PMID 38425649, 2024). "In psoriasis, proinflammatory cytokines, like interleukin-6 (IL-6), TNF-a, and interleukin-1 beta (IL-1β), play a pivotal role in driving the chronic inflammation observed in skin lesions." (PMID 38337350, 2024). "In support of the key role of IL-1β in IMQ-induced psoriasis, blockade of IL-1 receptor significantly diminished the production of IL-12p40 as well as IL-1β in psoriasis-induced skin lesions." (PMID 38704587, 2024). "APS improved psoriasis-like dermatitis in mice by inhibiting skin macrophage infiltration and reducing serum levels of TNF-α, IL-1β and IL-6." (PMID 39338338, 2024).
psoriasis (continued). "We found GPR15LG knockdown down-regulated the expressions of IL-1α, TNF-α, IL-1β and S100A7 in M5-treated HaCaT cells, suggesting a pivotal role of GPR15LG in keratinocyte-mediated inflammation in psoriasis." (PMID 38393364, 2024). "To further investigate the role of SLPI, S100A9, IL1B, CYBB, CXCL8, S100A12, and CXCL1 genes in the immune microenvironment of psoriasis, we examined inflammatory cell infiltration." (PMID 39014096, 2024). "The activation of IL-1β, pERK1/2, pNF-ĸB and pIĸB-α was observed in the DED mouse model, with mechanisms similar to those in psoriasis." (PMID 38254668, 2024). "The cytokines driven by NF-κB activation in psoriasis, including IL-17, TNF-α, IL-1β, and IL-6, were increased by IMQ exposure (p < 0.05)." (PMID 37111171, 2023). "The exact role of CARD18 in psoriasis remains to be elucidated as both CARD18 and IL-1β protein expression were found increased in lesional skin of psoriatic patients." (PMID 37325658, 2023). "When exposed to multiple triggers such as IMQ, stressed keratinocytes produce inflammatory cytokines, including IL-1β, IL-6, and TNF-α, which contribute to dermal DC activation and the initiation of psoriasis." (PMID 37717073, 2023). "Increased LAT1 expression is observed in keratinocytes and dermal infiltrating lymphocytes of patients with psoriasis, where LAT1 expression is upregulated by IL-23 and IL-1b." (PMID 37274280, 2023). "Previous research has demonstrated the inhibitory effect of GA on pro-inflammatory transcription factors, such as STAT3, RORγt, and NF-κB, or cytokines as IL-1β and TNF, which contribute to psoriasis development." (PMID 36754913, 2023). "The nanoformulations of CUR were majorly able to decrease psoriasis inflammatory symptoms, PASI, TNF-α, IL-17, IL-22 and IL-1β levels, C-C chemokine receptor type 6 (CCR6) expression, the proliferation of psoriatic cells and occurrence of psoriatic lesions." (PMID 36678859, 2023). "Psoriasis is an autoimmune inflammatory disease characterized by cytokines elevated, including TNF-α, IL-1β, IL-6, and IL-17A." (PMID 35860030, 2022). "In the pathogenesis of psoriasis, PRINS inhibits the expression of cellular inflammatory factors [e.g., interleukin (IL)-1α, IL-1β, IL-6, IL-8, and tumor necrosis factor-α) and thus affects inflammatory responses." (PMID 36187126, 2022). "Nicotine in tobacco smoke was the major alkaloid of cigarettes that activated the interleukin-1β (IL-1β), IL-2, IL-12, and tumor necrosis factor (TNF), which played a central role in psoriasis pathogenesis." (PMID 35646971, 2022). "Therefore, targeting IL-1β might be a promising strategy for treating psoriasis." (PMID 35153790, 2022). "Most recently, research efforts have demonstrated that patients with psoriasis have increased expression of the NLRP3 inflammasome in plasma, along with caspase-1 reactivity and elevated inflammasome-generated IL-1β and IL-18 concentrations." (PMID 35663672, 2022). "The mRNA levels of psoriasis‐related inflammatory factors such as TNF‐α, IL‐23, IL‐17A, IL‐1β and IL‐6 were measured by RT‐PCR." (PMID 35023281, 2022). "Lastly, IL-37 is able to inhibit IL-1β, IL-6, TNF, and chemokines such as CCL2, all involved in psoriasis." (PMID 36012744, 2022). "During this process, inflammatory cytokines: TNF‐α, IL‐1β, IL‐6, IL‐17a, and CXCL‐15 were infiltrated in skin and contributed to psoriasis." (PMID 35281792, 2022). "The levels of inflammatory TH17 cytokines (IL-17A, IL-22 and IL-23) and TH1 cytokines (IL-1β, IFN-γ and TNF-α) were also measured in the skin; psoriasis is considered to be regulated by TH17 and TH1 responses." (PMID 35562873, 2022). "In patients with psoriasis, the antagonism of TNF-α with etanercept also reduced the circulating levels of inflammatory and cardiovascular proteins, such as TNF-α, IL-1β, IL-6, and IL-8." (PMID 34674004, 2022).
psoriasis (continued). "The release of cytokines, such as IL-1β and TNF-α/IL-23/IL-17 by TLR4-mediated inflammatory immune cells is related to the severity of psoriasis." (PMID 36382932, 2022). "Uric acid contributes to the pathogenesis of psoriasis by initiating the NALP3 inflammasome, which drives IL-1β-mediated IL-17-committed T cell induction." (PMID 34373544, 2021). "The present study showed that alantolactone decreased the mRNA levels of TNF-α, IL-6, IL-1β, IL-8, IL-17A, and IL-23, thereby suppressing Th1- and Th17-mediated cytokines and improving IMQ-induced psoriasis-like skin lesions and inflammation status in mice." (PMID 34202301, 2021). "Four-weeks of VLCKD resulted in 10% weight loss, 50% reduction in PASI score, improvement of biochemical markers related to psoriasis (folic acid, vitamin B12, cortisol, bilirubin, calcium, LDL, cholesterol) and decreased IL-1β and IL-2 levels." (PMID 33499118, 2021). "3-HKA has protective effects in an experimental mouse model of psoriasis by decreasing skin thickness, erythema, scaling and fissuring, reducing TNF, IL-1β, IFN-γ, and IL-17 production, and inhibiting generation of effector CD8+ T cells." (PMID 34290243, 2021). "In psoriasis, MMP9 also significantly upregulates the mRNA levels of ICAM-1, IL1β and CXCL1 in vascular endothelial cells (VECs), which enables VECs interaction with more leukocytes." (PMID 34122426, 2021). "Although cytokines such as IL-17, IL-23, and IL-1β are mainly involved in the exacerbation of psoriasis, DC–T cell crosstalk through CD80/CD86 also affects psoriasis." (PMID 34421919, 2021). "Psoriasis is a hyperproliferative skin disease with a predominant Th1/Th17 response, with an upregulated concentration of multitude cytokines (TNF-α, IL-1β, IL-12, IL-17A, IL-22, IL-23, interferon-γ, and IL-13)." (PMID 34685480, 2021). "PPPs altered the mRNA expressions of the inflammatory cytokines (TNF-α, IL-6, and IL-1β) and improved the expressions of AQP3 and FLG in psoriasis-like mouse skin." (PMID 35153762, 2021). "MabE treatment inhibited the ear swelling of IMQ-treated mice, in addition to the mRNA expression of IL-17A, IL-1β and COX-2, which are known to be involved in the development and/or exacerbation of IMQ-induced psoriasis." (PMID 33836731, 2021). "Gene expression analysis in paw skin demonstrated increased expression of Tnf, Il1b, Il17a, and Il22 in mice injected with IL-23 EEV, consistent with the psoriasis-like changes seen on histology of the ears." (PMID 33983951, 2021). "Psoriasis patients exhibit enhanced circulating levels of IL-6, IL-18, IL-17A, IFN-γ, TNF, IL-1β, IL-27 and IL-29." (PMID 34068473, 2021). "Meanwhile, the expression of inflammatory factors (IL-1β, IL-6, TNF-α, IL-17, and IL-22) in serum and kidney tissue of psoriasis-like mice was significantly increased." (PMID 32090080, 2020). "In psoriatic patients, the expression of AIM2 and IL-1β is increased in keratinocytes from the skin lesion, and the activation of AIM2 in cultured keratinocytes leads to IL-1β release, suggesting that AIM2 is involved in the psoriasis pathogenesis." (PMID 32295112, 2020). "The positive staining for both TNF-α and IL-1β was increased in the IMQ group in comparison to the normal group, indicating high expression of pro-inflammatory cytokines in psoriasis plaque." (PMID 32708987, 2020). "IL-1β, IL-6 and TNF-α are important proinflammatory cytokins, especially TNF-α, involving in psoriasis pathogenesis." (PMID 33081840, 2020). "Inflammatory markers, that are typical in psoriasis, like TNF-α, IL1β, and mast cell degranulation, as well as occludin and ZO-1 tight junctions (TJs), were examined." (PMID 32708987, 2020). "The participation of macrophages in the pathogenesis of psoriasis has been previously suggested with a key role for TNF and IL-1β." (PMID 32269570, 2020).
psoriasis (continued). "The expressions of crucial inflammatory mediators (including IL-1β, IL-2, IL-6, IL-10, IL-17, IL-22, IL-23, IFN-γ, TNF-α) in skin tissues were measured by ELISA due to the import role of inflammatory cytokines in psoriasis." (PMID 31181689, 2019). "Before treatment and after 3 months of therapy, Psoriasis Area and Severity Index (PASI) score and serum IL-1β were measured to evaluate the outcome of treatment." (PMID 31252651, 2019). "IL-1β and IL-23 are induced during IMQ-induced psoriasis and trigger the expression of Il17a from γδ T cells." (PMID 31622280, 2019). "Several genes reported to be involved in psoriasis pathogenesis including S100A9, S100A8, PTPN22, PTPN6, LAMA4, IL1B and IL12RA were involved in many of these enriched biological processes." (PMID 30092825, 2018). "Altogether, besides IL-1β and TNF-α, C5a is likely to play a role in the early neutrophil predominant and auto-inflammatory phase of psoriasis." (PMID 29713318, 2018). "Overall, we showed that CCN1 increased IL-1β production via p38 MAPK signaling, indicating a role for CCN1 protein in regulating inflammation in psoriasis." (PMID 28266627, 2017). "In conclusion, the present study reveals a novel mechanism for CCN1 in regulating IL-1β expression via p38 MAPK signaling in keratinocytes, which contributes to the inflammatory microenvironment of psoriasis." (PMID 28266627, 2017). "In the current study, we demonstrated that psoriasis-like inflammation requires moDCs, which produce the critical cytokines, TNF and IL-1β, and depend on CCR6 for their optimal accumulation in the skin." (PMID 27982014, 2016). "Many immune-derived cytokines, including IL-23, IL-17A, IL-20, IL-22, IL-1β, IL-6, and TNF-a, are involved and interact as a network in the pathogenesis of psoriasis." (PMID 23825622, 2013). "Migration of epidermal Langerhans cells (LCs) in response to the cytokines interleukin (IL)-1β and tumour necrosis factor (TNF)-α is impaired in uninvolved skin of patients with early-onset psoriasis." (PMID 21933242, 2012). "Serum tumor necrosis factor alpha (TNF-α), interleukin 1-beta (IL-1β), high-sensitivity C-reactive protein (Hs-CRP), sialic acid, and Sialic acid binding Ig-like Lectin-14 (Siglec-14) levels were investigated in controls and psoriasis patients." (PMID 41598424, 2026). "After eight weeks of treatment, 11 out of 12 patients showed a 20–80% improvement in the Psoriasis Area and Severity Index (PASI), which was accompanied by a decreased expression of pro-inflammatory cytokines, including IFN-γ, IL-8, IL-12, TNF-α, and IL-1β." (PMID 40731810, 2025). "While its role in psoriasis and obesity remains unexplored, NTBF strains have shown anti-inflammatory effects in vitro and in vivo, notably through modulation of cytokines such as IL-10, IL-1β, and IL-6, and downregulation of the NF-κB pathway." (PMID 41226468, 2025). "Notably, genes such as Nlrp3, Casp1, Casp4, IL-1β, IL-18, and Stat1 had high degree values, indicative of their significant position in the PPI network and potential targets for FZHFZY treatment of psoriasis." (PMID 41383588, 2025). "Furthermore, RT-qPCR analysis of pyroptosis-associated inflammatory cytokines revealed significantly increased expression of IL1β, IL6, and TNFα in psoriasis-derived MDMs compared to healthy controls." (PMID 40722833, 2025). "In addition, in the psoriasis group induced by IMQ, the levels of IL-1β, IL-6, TNF-α, and IL-17A were higher in the cko group than those in the wt group, especially IL-1β and IL-6 (p < 0.05)." (PMID 40430037, 2025). "Validation through clinical psoriasis patient samples revealed that, compared to non-lesional tissue, the expression levels of IL-1β and NLRP3 were remarkably upregulated in lesional tissue." (PMID 41383588, 2025). "Notably, the module score also incorporated proinflammatory cytokines (IL17A, IL1B, IL22, IL23, and IFNG) which were upregulated in lesional psoriasis, providing context for the regulation of plakin family members." (PMID 40746860, 2025).